TP53TG3E (TP53 target 3 family member E)
Gene: Protein-coding gene on chromosome 16 (33,304,306 to 33,306,945, forward strand). Ensembl gene ENSG00000275034.
Subcellular location: Cytoplasm; Nucleus
Subcellular location (Human Protein Atlas): Centriolar satellite
Gene Ontology:
Cellular component: cytoplasm; nucleus
Homologues: Paralogues in human: TP53TG3 (100% identical), TP53TG3B (100% identical), TP53TG3C (100% identical), TP53TG3D (100% identical), TP53TG3F (100% identical).